ACADS (acyl-CoA dehydrogenase short chain)
Description:
Short-chain specific acyl-CoA dehydrogenase is one of the acyl-CoA dehydrogenases that catalyze the first step of mitochondrial fatty acid beta-oxidation, an aerobic process breaking down fatty acids into acetyl-CoA and allowing the production of energy from fats (By similarity). The first step of fatty acid beta-oxidation consists in the removal of one hydrogen from C-2 and C-3 of the straight-chain fatty acyl-CoA thioester, resulting in the formation of trans-2-enoyl-CoA (By similarity). Among the different mitochondrial acyl-CoA dehydrogenases, short-chain specific acyl-CoA dehydrogenase acts specifically on acyl-CoAs with saturated 4 to 6 carbons long primary chains.
Synonyms: SCAD; ACAD3
Tractability: Small molecule: a structure with a bound ligand is known; it has a binding pocket of medium quality. PROTAC: ubiquitination databases record sites on it; its protein half-life has been measured.
Gene: Protein-coding gene on chromosome 12 (120,725,774 to 120,740,009, forward strand). Ensembl gene ENSG00000122971.
Subcellular location: Mitochondrion matrix
Subcellular location (Human Protein Atlas): Mitochondria; Centrosome; End piece; Mid piece; Nucleoplasm; Principal piece
Pathways (Reactome):
Metabolism: Beta oxidation of butanoyl-CoA to acetyl-CoA; Beta oxidation of hexanoyl-CoA to butanoyl-CoA
Gene Ontology:
Molecular function: acyl-CoA dehydrogenase activity; protein binding; short-chain fatty acyl-CoA dehydrogenase activity; flavin adenine dinucleotide binding; medium-chain fatty acyl-CoA dehydrogenase activity; oxidoreductase activity, acting on the CH-CH group of donors
Biological process: fatty acid beta-oxidation using acyl-CoA dehydrogenase; butyrate catabolic process; fatty acid beta-oxidation
Cellular component: mitochondrion; nucleus; mitochondrial matrix
Genetic constraint (gnomAD): Loss-of-function variants: 28 observed, 45.08 expected, observed/expected ratio (o/e) 0.62, 90% interval 0.46 to 0.85. The upper end of that interval is the gene's LOEUF score, 0.85, which puts it in group 3 of 6, group 1 being the genes least tolerant of losing a copy. Missense variants: 528 observed, 580.35 expected, observed/expected ratio (o/e) 0.91, 90% interval 0.85 to 0.98. Synonymous variants: 236 observed, 234.65 expected, observed/expected ratio (o/e) 1.01, 90% interval 0.9 to 1.12.
Gene-disease validity (ClinGen):
ClinGen rates the evidence that ACADS causes each of these diseases.
short chain acyl-CoA dehydrogenase deficiency (autosomal recessive): Definitive.
Homologues: Orthologues: chimpanzee ACADS (99% identical), macaque ACADS (99% identical), dog ACADS (92% identical), guinea pig ACADS (91% identical), mouse Acads (91% identical), rat Acads (90% identical), rabbit ACADS (90% identical), pig ACADS (80% identical), zebrafish acads (73% identical), Drosophila melanogaster Arc42 (69% identical), tropical clawed frog acads (60% identical), Caenorhabditis elegans acdh-1 (37% identical), and 7 more. Paralogues in human: ACADSB (39% identical), ACAD9 (37% identical), IVD (35% identical), ACADM (35% identical), ACAD8 (35% identical), ACADVL (34% identical), ACADL (31% identical), GCDH (29% identical), ACAD11 (29% identical), ACAD10 (27% identical), ACOX3 (25% identical), ACOXL (22% identical), and 2 more.
Diseases named in the same sentence as ACADS in open-access papers:
ACADS is named in the same sentence as 51 diseases in open-access papers, as found by Europe PMC text mining. Sharing a sentence is not in itself a finding about the gene and the disease. The quoted sentences say what the papers report.
SCAD deficiency (14 papers, 2010 to 2026). "Mutations in the ACADS gene cause SCAD deficiency (SCADD), a disorder with remarkably heterogeneous clinical presentation." (PMID 41898520, 2026). "Biallelic variation in the ACADS gene can cause short-chain acyl CoA dehydrogenase deficiency, which can lead to a variety of phenotypes including fatty acid oxidation disorders." (PMID 40281739, 2025). "Short-chain acyl-CoA dehydrogenase deficiency (SCAD)-related ACADS gene hotspot mutations are c.164C > T (33.33%) and c.1031A > G (33.33%)." (PMID 36246604, 2022). "Most patients with SCAD deficiency carry two mutation alleles of the two common variants, or harbor one of them in combination with a rare variant in ACADS gene, and the hotspot in Ashkenazi Jewish patients is a pathogenic c.319C > T mutation." (PMID 31737040, 2019). "Pathogenic mutations in ACADS have been identified in patients with SCAD deficiency, whereas others carry two ACADS polymorphisms (G625A and C511T) that are considered susceptibility variants." (PMID 26839416, 2016). "The rs1799958 SNP (G>A) in ACADS results in the conversion of glycine to serine and associates with the short chain acyl-CoA dehydrogenase deficiency that is characterized by lipid storage myopathy and muscle weakness." (PMID 20180986, 2010). "The short-chain acyl-CoA dehydrogenase deficiency (SCADD) is caused by variants of ACADS gene." (PMID 40225143, 2023). "Some hotspot variants resulting in the defect of enzymes have been identified in patients with IMEs, such as ACADS variants c.511C > T and c.625G > A for short chain acyl-CoA dehydrogenase deficiency (SCADD; MIM# 201470), PAH variant c.728C > A for phenylketonuria (PKU; MIM# 261600), and so on." (PMID 31737040, 2019). "In addition, mutations in ACADS gene were detected in four cases of short-chain acyl-CoA dehydrogenase deficiency, and two of them were accompanied with glutaric acidemia (type I or type II ) carried mutations in the GCDH and ETFDH genes, respectively." (PMID 29731766, 2018).
hepatocellular carcinoma (7 papers, 2019 to 2025). A malignant tumor that arises from hepatocytes. "In humans, ACADS, which is mainly expressed in fat tissue, liver and intestine, was found to be associated with hepatocellular carcinomas." (PMID 35748965, 2022). "ACADS was indicated as a potential methylation biomarker in hepatocellular carcinomas and was associated with cancer cell proliferation and metastasis." (PMID 34790035, 2021). "DNA methylation of ACADS has been established as a key regulatory mechanism governing proliferation and metastasis in hepatocellular carcinoma." (PMID 41415282, 2025). "Therefore, we created a mouse model of HCC using Hepa1-6 cells, a mouse hepatoma line, to explore the potential effects of ACADS on tumour microenvironment (TME) reprogramming." (PMID 39800718, 2025). "ACADS, as one of the key metabolic genes related to the metabolic response involved in carcinogenesis, is regulated by DNA methylation and can be used as a potential methylation biomarker related to the proliferation and metastasis of hepatocellular carcinoma." (PMID 33042807, 2020). "However, the specific role of ACADS in hepatocellular carcinoma (HCC) pathogenesis remains poorly understood." (PMID 39800718, 2025).
breast carcinoma (4 papers, 2013 to 2026). "Adiponectin could repress the proliferation of breast cancer cells in vitro, and decreased the expression level of ACADS meanwhile, which indicated that ACADS could be a promising biomarker in breast cancer." (PMID 34790035, 2021). "The genes containing the most significant SNPs for breast cancer ranged widely in apparent function with GWAS associations reported with SNPs in CFB (complement factor B) for age-related macular degeneration, BAZ2A for platelet counts and ACADS for metabolic traits." (PMID 23555315, 2013).
colon cancer (3 papers, 2019 to 2023). "Data from TCGA database analyses also revealed that approximately 50% of colon cancer patients had elevated ACAD9 mRNA levels, while the majority of patients displayed a reduction in ACADS mRNA." (PMID 31623618, 2019).
colorectal cancer (3 papers, 2018 to 2022). A primary or metastatic malignant neoplasm that affects the colon or rectum. "By subcutaneously injecting colorectal cancer cells (CT26) into Balb/c and Balb/cByJ mice to construct a mouse subcutaneous tumor model, we observed that the deletion of ACADS in mice resulted in the significantly accelerated growth of colorectal cancer." (PMID 36552870, 2022). "The subcutaneous injection of colorectal cancer cells into Balb/c and Balb/cByJ mice demonstrated that the deletion of ACADS promoted the growth of colorectal cancer." (PMID 36552870, 2022). "The present findings elucidated a new mechanism of ACADS in regulating the immune escape of colorectal cancer." (PMID 36552870, 2022). "However, the expression level and prognostic value of ACADS in colorectal cancer (CRC) remain unclear." (PMID 34790035, 2021). "Therefore, we used the correlation of the expression level of genes with the prognosis of colorectal cancer patients as an evaluation index, and finally identified eight critical enzymes of amino acid metabolism in colon TAMs, namely, ACADM, ACADS, GPX4, GSR, HADH, HMGCL, HMGCS1 and IDH1." (PMID 36552870, 2022).
developmental delay (3 papers, 2011 to 2020). "Among these P2RX2 and ACADS are noteworthy for the developmental delay and behavioral and social problems presented in our patient." (PMID 32578677, 2020).
Obesity (3 papers, 2018 to 2026). Accumulation of substantial excess body fat. "The expression of ACADS has a negative correlation with BMI (p = 2.91 × 10−12), and the alternate allele is associated with an increase in expression of ACADS, suggesting that this allele has a protective effect against obesity." (PMID 29666371, 2018). "A previous study identified ACADS as an obesity‐related gene in humans, and adipose expression of ACADS was robustly correlated with BMI." (PMID 41077621, 2026). "Proteins involved in energy metabolism, such as AK2, ADH1B, ACADS, and GCDH, were downregulated in patients with obesity, suggesting impaired lipid metabolism and mitochondrial dysfunction." (PMID 41077621, 2026).
Alzheimer disease (2 papers, 2025 to 2026). A progressive, neurodegenerative disease characterized by loss of function and death of nerve cells in several areas of the brain leading to loss of cognitive function such as memory and language. "Given the central role of mitochondrial fatty acid β-oxidation (FAO) in brain energy homeostasis and its dysfunction in Alzheimer’s disease (AD), we sought to directly assess the functional capacity of this pathway by measuring the enzymatic content of key Acyl-CoA Dehydrogenases (ACADs)." (PMID 41300478, 2025). "In replication analyses, 21 genes showed nominal support in UK Biobank and Alzheimer's Disease Genetics Consortium (ADGC) cohorts, with eight genes (TREM2, ACADS, MFSD12, NUP210L, PIEZO2, PSEN1, SMURF2, AKAP13) supported under identical masks." (PMID 41960309, 2026).
carnitine deficiency (2 papers, 2024 to 2025). "Among the top ten common variants, DUOX2, SLC22A5, PAH, and ACADS were associated with CH, primary carnitine deficiency, hyperphenylalaninemia, and short-chain acyl-CoA dehydrogenase deficiency, respectively." (PMID 38575986, 2024).
Anxiety (1 paper, 2024). Intense feelings of nervousness, tension, or panic often arise in response to interpersonal stresses. "On the other hand, the false-positive results due to ACADS gene variants may impose a burden on follow-up efforts, cause unnecessary anxiety for families, and lead to unnecessary interventions." (PMID 39449356, 2024).
bladder cancer (1 paper, 2021). "As a part of a novel multi-dimensional transcriptome signature, ACADS participated in the prognosis prediction in bladder cancer." (PMID 34790035, 2021).
colorectal tumors (1 paper, 2019). "Previous metabolomics study discovered that palmitate and oleate levels increase in MYC-driven colorectal tumors, while enzymes involving fatty acid oxidation, including ACADS, are down-regulated." (PMID 31623618, 2019).
diabetes (1 paper, 2011). "Further investigation is needed before conclusive remarks can be appointed to the variants in ACADS and ACADM and their putative involvement in the pathogenesis of diabetes." (PMID 21211036, 2011). "The impact of ACADS rs2014355 and ACADM rs11161510 on OGTT-derived diabetes-related quantitative traits was evaluated in a random sample of glucose-tolerant individuals from the Inter99 cohort." (PMID 21211036, 2011).
fatty liver (1 paper, 2024). "Similar to our findings, Zengpeng and colleagues demonstrated that dietary genistein supplementation resulted in the upregulation of gene transcription associated with fatty acid beta-oxidation, including PPARα, PPARδ, ACOT8, ACAD8, and ACADs in the liver of laying hens induced fatty liver." (PMID 38540097, 2024).
glaucoma (1 paper, 2016). Increased pressure in the eyeball due to obstruction of the outflow of aqueous humor. "Two variants (p.A10S in TRMU and.G185S in ACADS) also appear in HGMD, and are flagged as “clinically associated” in dbSNP, p.R76K in MYOC was believed to contribute to glaucoma in a di-genic inheritance and p.G5R in LIPA was shown in a functional assay to cause reduced enzymatic activity." (PMID 27175728, 2016).
Hypoglycemia (1 paper, 2011). A decreased concentration of glucose in the blood. "Under fasting states or other stressing conditions such as fever, defects of ACADS have been linked to hypoglycemia." (PMID 21211036, 2011).
leukopenia (1 paper, 2021). "In this study, two key enzymes, the BCKDHA and ACADS enzyme levels in leukopenia, significantly increased in the BCAAs catabolism pathway." (PMID 34759816, 2021). "Molecular biology verification results showed that Lvjiaobuxue granule can significantly reduce the key metabolic enzymes ACADS and BCKDHA in the catabolism of BCAAs, thereby playing a role in the treatment of leukopenia." (PMID 34759816, 2021).
mood disorder (1 paper, 2010). A cognitive disorder a disturbance in which the person's mood is hypothesized to be the main underlying feature. "ACADS, acyl-Coenzyme A dehydrogenase, C-2 to C-3 short chain, is an enzyme participating in the fatty acid β-oxidation and has not previously been reported to associate with mood disorder or AUD." (PMID 20180986, 2010).
neuroblastoma (1 paper, 2025). Neuroblastoma (NB) is the most common solid, extracranial childhood tumor. "These genes included neuroblastoma-amplified sequence (NBAS), ETS variant transcription factor 6 (ETV6), transmembrane protein 165 (TMEM165), collagen type IV alpha-3-binding protein (C43BP), serine/threonine-protein phosphatase 5 (PPP5), and short-chain specific acyl-CoA dehydrogenase (ACADS)." (PMID 39400548, 2025).
ovarian carcinoma (1 paper, 2021). A malignant neoplasm originating from the surface ovarian epithelium. "In addition, mitochondrial phosphoproteomics and immunoprecipitation-western blot experiments identified and confirmed that phosphorylation occurred at residue Ser70 in protein HSP60, which might regulate protein folding of ALDH2 and ACADS in ovarian cancers." (PMID 34557266, 2021).
Rb (1 paper, 2019). "This is the first study suggesting that these genes, FGFR4, NQO1, ACADS CX3CR1, GBE1, KRT85, and TYR genes, may play a role in the etiology of Rb." (PMID 31207142, 2019).
cancer (7 papers, 2019 to 2026). A tumor composed of atypical neoplastic, often pleomorphic cells that invade other tissues. "Expression of ACADS was found to be significantly associated with clinical cancer stages and the consensus molecular subgroups (CMS) constituent ratio in CRC patients." (PMID 34790035, 2021). "The expression of ACADS was associated with clinical cancer stages and the ratio of CMS based on the analysis of TCGA and GEO database." (PMID 34790035, 2021). "To determine the specific CpG island site in the ACADS promoter that regulates its expression in cancer, we comprehensively analysed Me-DIP sequences from TCGA and our centre." (PMID 39800718, 2025). "The ACADS promoter was hypermethylated in the majority of solid tumours and negatively correlated with mRNA expression in a pan-cancer analysis, and we confirmed increased methylation of the ACADS promoter in HCC cells using BSP." (PMID 39800718, 2025). "Altered metabolism has become an important characteristic of cancer, and acyl-CoA dehydrogenase short-chain (ACADS), a regulator of lipid synthesis, is involved in carcinogenesis-associated metabolic pathways." (PMID 39800718, 2025). "ACADS regulates key cellular processes to facilitate tumorigenesis and has been identified as a promising target for cancer therapy by numerous studies." (PMID 37994323, 2023). "Materials and methods: A thorough comparative analysis of 282 cancer samples with 47 normal samples from GEO datasets resulted in the observation that that the level of ACADS was significantly downregulated in HCC." (PMID 31652420, 2019). "Similarly, there was a positive relationship between ACADS expression and DC infiltration in cancer." (PMID 39800718, 2025). "ACADs are key enzymes involved in carcinogenesis-associated metabolic pathways, and many studies have revealed that ACAD could be a novel biomarker for cancer." (PMID 39800718, 2025). "Further studies identified methylation sites of ACADs and differences in the expression of methylation levels of ACADs between cancer and normal tissues, suggesting that epigenetic alterations in ACADS may be involved in forming this phenomenon." (PMID 37545527, 2023). "Expression levels of ACADS in 63 CRC cell lines were maintained at 2-4, which was relatively higher than other cancer cell lines." (PMID 34790035, 2021).